MYC (MYC proto-oncogene, bHLH transcription factor)
Diseases named in the same sentence as MYC in open-access papers (continued):
Sharing a sentence is not in itself a finding about the gene and the disease.
cancer (continued). "A combination of CAPE and Docetaxel induces CaP cell deaths and suppresses cancer proliferation and progression by downregulating the expression of anti-apoptotic markers and caspase activation, Bcl-2, AKT-2, c-MYC, and pyruvate kinase M2." (PMID 37895357, 2023). "The compound L755507 efficiently blocks MYC/MAX heterodimerization, leading to decreased MYC target gene expression and induction of programmed cell death in cancer cells." (PMID 36969025, 2023). "In general, on the basis of our USP45 discoveries on its MYC deubiquitination and α-mangostin inhibition, suppressing USP45 has opened a new window for suppressing cancer development, stemness and drug resistance." (PMID 36765885, 2023). "In summary,these results demonstrate the anti‐cancer properties of Z363, a small molecule that is co‐regulated by TAF10 and MYC." (PMID 36639831, 2023). "The most extensively investigated oncomiR hsa-miR-17-92 cluster, involved in B-cell development, is dysregulated in different cancer entities and EBV-infected B-cells and is known to be under the transcriptional control of MYC." (PMID 37766215, 2023). "We then compared amplifications around MYC, ERBB2 and EGFR in the whole chromosome view in corresponding highly amplified cancer tissues." (PMID 37298484, 2023). "Western blot results showed that c-MYC expression was comparable in c-MYC WT, c-MYC S405A, and c-MYC S405E cancer cells." (PMID 37596667, 2023). "Luciferase reporter assay was conducted to examine the translation activity of GPX4 promoter, and immunohistochemistry (IHC) was conducted to analyze the levels of c-MYC, Ki-67 and AR in TQB3720-treated cancer tissues." (PMID 36744249, 2023). "MYC is one of the well-characterized transcription factors, including OCT4, SOX2, NANOG, KLF4, in cancer stem cell establishment, maintenance, and functions." (PMID 36941257, 2023). "Here I discussed the mutually inseparable relationships and cooperation of KRAS, MYC, and ARF6 in cancer malignancy and immune evasion." (PMID 37158894, 2023). "c-MYC was shown to regulate LAT1 by transcriptional activation and binding to the promoter region of LAT1 in cancer cells." (PMID 37110218, 2023). "HECTD3, a member of the third subfamilies of HECT ligases, was validated to target and ubiquitinate caspase-9, c-MYC, and TRAF3 in cancers, already." (PMID 37031183, 2023). "Specifically, 10058-F4 inhibited MYC/MAX heterodimerization and demonstrated cytotoxic activity and apoptosis induction activities in a variety of cancer cell lines." (PMID 37111592, 2023). "By the way, an average proportion of GAs for known oncogenes (e.g., KIT, MYC, CTNNB1, MDM2 and APC) in the same pan-cancer cohort ranges from four to 9%." (PMID 37373333, 2023). "Here, we define the tissue distribution of genetic alterations in PRKACA and PRKAR1A that result in PKA activation in cancer and map the multiple conserved pathways downstream of oncogenic PKA signaling, many of which impinge on the expression of c-MYC." (PMID 36692000, 2023). "The MYC oncogene with its two paralogues MYCN and MYCL is one of the most important oncogenes across many human cancer types, including a subgroup of pediatric CNS tumors." (PMID 37173990, 2023).
cancer (continued). "Given these distinct ALAN outputs of the MYC ALAN network signatures across multiple cancers and within cancer subtypes, we used GSEA to determine if the ALAN network signature was enriched of MYC activity." (PMID 37059746, 2023). "Next, we identified significantly enriched KEGG (Pathways in cancer and PI3K/Akt signaling pathway) and GO (GO:0000122, GO:0045944 and GO:0045893) terms, and identified eight genes (EDN1, CCND1, MYB, MYC, RUNX1, ITGA6, IL6 and FGF2." (PMID 36978140, 2023). "Z363 exerts an anti‐cancer effect on cancer cell and xenograft models by co‐regulating TAF10 and MYC." (PMID 36639831, 2023). "BET inhibitors (BETi) have emerged as a novel class of epigenetic drugs that acts as an anti-cancer agent by blocking VEGF production and down-regulating MYC expression in different types of cancer, including BC." (PMID 38268926, 2023). "Numerous cancers exhibit deregulation of the MYC family of oncogenes, which includes c-MYC, MYCN, and MYCL, and this is frequently correlated with a poor outcome." (PMID 37239815, 2023). "The GREAT analysis showed enrichment of both positively and negatively age-related CpG sites in mortality or aging gene sets, cancer and targets of three Yamanaka factors: SOX2, MYC and OCT4." (PMID 37563227, 2023). "We also found that a transcription factor and MYC target, GATA2, is a downstream target for the anti-cancer effects of the WS6 analogues." (PMID 36980710, 2023). "The average gene alteration frequency was <2%, which is low compared to those of protooncogenes (i.e., MYC, ERBB2, RAS) that typically show sporadic gene amplification frequencies of > 20% in many cancers." (PMID 37268816, 2023). "We have previously shown that PPRHs are a valuable tool for gene silencing of relevant cancer targets such as dihydrofolate reductase, survivin, BCL2, TOP1, mTOR, MDM2, and MYC." (PMID 37108234, 2023). "The reported deubiquitinases of MYC include USP22, USP28, USP29, USP36 and USP37, and they enhance cancer stemness via BMI1, LSD1 Snail and CEP63 stabilization, respectively." (PMID 36765885, 2023). "Western blot analysis revealed that MYC and ATF4 were highly expressed in NDCs derived from cytotoxin‐treated cancer cells and tumors derived from cytotoxin‐treated HeLa‐Luc NDCs." (PMID 36739602, 2023). "Here discussed are that KRAS, MYC, and ARF6 are biochemically and functionally closely related with each other in promoting cancer malignancy and immune evasion." (PMID 37158894, 2023). "LOXL2 associates with and catalyses H3K36ac deacetylation thus blocking H3K36ac-dependent transcription of genes, including MYC proto-oncogene, BHLH transcription factor (MYC), cyclin D1 (CCND1), HIF1A, and CD44, thereby restricting cancer cell proliferation." (PMID 37762708, 2023). "Among these 70 coexpressed genes, we noticed two particular ones: MYC and MMP2, two well-recognized malignancy markers closely related to cancer cell proliferation, survival and invasion." (PMID 37667197, 2023). "Regarding copy number alterations, the amplification of locus 8q24.21, where oncogene MYC and stemness factor POU5F1B reside, was similarly present in the two claudin-low groups, but more prevalent in basal ER-negative/HER2-negative cancers." (PMID 37345027, 2023). "Two groups have shown that MYC (both MYC and MYCN) can inhibit BMAL1 and CLOCK function in cancer cells and disrupt the circadian dynamics of the core clock molecules." (PMID 37601651, 2023). "Considering this, we propose that SSO‐QPOP can guide the co‐development of effective cancer therapeutics, such as CHK1 and BRD4 inhibitors against MYC‐driven HCC." (PMID 36684069, 2023). "Patchouli alcohol is also known to have anticancer properties because it can inhibit the growth of cancer cells through the mechanism of inhibiting HDAC2 enzyme expression, downregulation of c-MYC, and activation of the NF-κB pathway." (PMID 36903266, 2023).
cancer (continued). "In the present work, we employ MYC inhibition by shRNA and by Omomyc to investigate MYC’s role in regulating RNAPII post-translational modifications, RNAPII distribution, and gene expression in cancer cells." (PMID 36830948, 2023). "Therefore, multiple connections between c-MYC and cholesterol may play a role in cancer." (PMID 37705742, 2023). "Due to the dysregulation of MYC, the activity of ODC is typically upregulated in cancer, resulting in an increase in polyamine levels that promote the rapid proliferation of tumor cells." (PMID 38049863, 2023). "The results of this study showed that TK1 was positively correlated with cell cycle- and proliferation-related pathways, such as MYC target and MTORCI signaling pathway, in multiple cancer types." (PMID 37767092, 2023). "In the high-risk group, the cuproptosis-related genes signature activated G2M checkpoint, E2F target, and MYC target and DNA repair signaling, according to the GSVA analysis of cancer hallmarks." (PMID 36750831, 2023). "As expected, we confirmed that TK1 was positively correlated with cell cycle- and proliferation-related pathways, such as MYC target and MTORCI signaling pathway, in multiple cancer types." (PMID 37767092, 2023). "The overlap between MYC and the known cellular functions of CDK12, as well as the requirement of CDK12 for optimal processing of MYC, collectively indicates CDK12 is a potential therapeutic target for MYC‐dependent cancers." (PMID 36670542, 2023). "The bioinformatic analysis of TCGA suggests that combinations of MYC and KLF4 as well as OCT4 and MYC were important for permissive cancers." (PMID 37515162, 2023). "Our findings concurred with those of another study showing that the suppression of c-MYC by CPI-0610, a small-molecule bromodomain and extra-terminal protein inhibitor, induced G0/G1 arrest as well as apoptosis in MM, leading to cancer regression." (PMID 37627164, 2023). "The MYC gene cluster, which consists of the c-MYC (MYCC), MYCN, and MYCL genes, has been intensively studied in cancer and developmental biology." (PMID 38049863, 2023). "In various types of cancer cells and solid tumor tissues, high CD47 protein levels, which are mainly triggered by the transcription factor MYC, have been observed." (PMID 36966168, 2023). "While targeting c-MYC and/or MYCN for cancer treatment is a major challenge, these proteins represent a potential group of targets for which drugs are already available or are in development." (PMID 37760568, 2023). "Finally, MYC-driven cancers may be particularly responsive to such therapies." (PMID 36897988, 2023). "It is observed that high MYC levels and EMT often co-occur in cancer, and they can contribute to the same characteristics of later stage tumors." (PMID 37601651, 2023). "The resulting heatmap revealed significant enrichment of cell proliferation-related signaling pathways, including MYC, mTORC1, Mitotic spindle, G2M, and E2F pathways, in the NUSAP1-high patients across almost all cancer types." (PMID 37781040, 2023). "For instance, proliferation- and cell survival-promoting TFs, such as MYC, Jun-, FOS- and E2F family TFs, were found to have significantly increased activity across the three cancer types." (PMID 37843125, 2023). "By performing correlation analysis, we revealed that CLS was highly correlated with some cancer-related pathways, such as mitotic spindle, DNA repair, G2/M checkpoint, PI3K-AKT-MTOR signaling, MTORC1 signaling, E2F targets and MYC targets." (PMID 36761763, 2023).
cancer (continued). "In accordance, ATF1 is positively correlated with both pluripotent (33/33, 23/33 of cancer types for MYC and NANOG, respectively) and mitochondrial regulators (33/33 of cancer types for both TFAM and NRF1) in TCGA cohorts." (PMID 37463926, 2023). "Given MYC and SMAD4 are known to be modulated by statins, the phenotypic switch caused by high and low doses of the same uPAR modulator may become an interesting research topic to elucidate whether these cancer driver genes could also serve as surrogate markers in anti-cancer therapies." (PMID 37895906, 2023). "The deregulated activity of both c-MYC and MYCN has also been shown to play a critical role in maintaining a stem-like state in cancer cells by blocking differentiation pathways and promoting the expression of self-renewal and pluripotency genes." (PMID 37760568, 2023). "In human cancers, FAM83H is involved in cancer progression in conjunction with MYC, the Wnt/β-catenin pathway, and the PI3K/AKT pathway." (PMID 37761326, 2023). "Given the function of MTBP in proliferation, DNA replication, and cellular transformation as well as the connection between MTBP and MYC, it would be expected that MTBP has a critical role in cancer." (PMID 35741402, 2022). "As specific inhibition of CDK9 has been shown to induce downstream depletion of key oncoproteins including MCL-1 and c-MYC, targeting this CDK protein has also become of interest as a cancer therapy." (PMID 35936751, 2022). "LncRNA-SNHG15 regulated the expression of downstream genes including MYC, NRAS, BAG3, and ERBB3, which are closely related to cancer progression." (PMID 35617032, 2022). "The MYC gene and the MIR125B microRNA are directly involved in establishing the specific programs of gene expression in cancer cells, comprising almost all aspects of cancer biology, such as proliferation, apoptosis, invasion/metastasis, and angiogenesis." (PMID 36553455, 2022). "The MYC family consisting of MYC, NMYC and LMYC is a master regulator of various important cellular processes, thus playing a crucial role in tumorigenesis of various cancer types." (PMID 35269569, 2022). "In conclusion, we identified recurrent targeting of several cancer genes such as PDL1 and MYC upon HPV integration, suggesting a role of altered gene expression by HPV integration during HNSCC carcinogenesis." (PMID 35398964, 2022). "Hence, while the list of clinically relevant CDK inhibitors is steadily growing, whether MYC expression and/or activity may be used to predict the response of cancer cells to these molecules remains an important open question that needs to be systematically addressed." (PMID 36214609, 2022). "ERK/c-MYC and ERK/Cyclin D1 signaling are well known in promoting proliferation and migration in cancer cells, and HTR1E has been found in human cancer cells." (PMID 35328535, 2022). "Thus,we hypothesized that MYC-driven cancers would be more sensitive toActD." (PMID 35977718, 2022). "Our pan-cancer analysis found that amplifications in HSF1 and MYC genes (both situated at this locus) co-occurred in a high percentage of cases." (PMID 35311075, 2022). "It has also been reported that alterations of m6A levels of MYC and EGFR are involved in the regulation of cancer pathogenesis and progression." (PMID 35874897, 2022). "MYC is a typical oncogene controlled by SE-mediated transcription-regulating mechanisms, and WNT signaling activates MYC expression in cancer cells." (PMID 35277481, 2022). "Next, we examined the co-amplification and co-expression of EXOSC4 with HSF1, MYC, and POU5F1B, which are located on chromosomes 8q24.3, 8q24.21, and 8q24.21, respectively, in nine different cancer types." (PMID 35008922, 2022).
cancer (continued). "In breast cancer patients (n = 421) whose cancers have high levels of MYC mRNA expression, concurrent high expression of both MYC and MTBP mRNA conferred worse survival compared to those with high MYC and low MTBP expression (p = 0.0314)." (PMID 35741402, 2022). "The transcription of LDHA is mainly regulated by two transcription factors, i.e., HIF1 and c-MYC (Avian myelocytomatis virus oncogene cellular homolog), which collaborate to activate LDHA transcription in numerous cancer cells." (PMID 36551514, 2022). "Conversely, in response to hypoxia and oncogenic signals, like MYC and PI3K, cancer cells predominantly utilize glycolysis to support rapid growth and genome replication, even under abundant oxygen." (PMID 36200045, 2022). "In DU145 cells, TUBB4A KO or MYH9 KD increased the expression of GSK3β but decreased the expression of nuclear β-catenin and its downstream targets, cyclin D1 and c-MYC, suggesting TUBB4A/MYH9-mediated GSK3β/β-catenin signaling in human cancer cells." (PMID 35589707, 2022). "Several transcription factors, such as STAT1/3, HIF-1α, NF-κB, AP1, and MYC, and various cytokines, including IFN-γ, and TGF-β, have been shown to regulate the expression of the PD-L1 gene in cancer cells." (PMID 35626102, 2022). "For example, the G4 in c-MYC is the target of several G4BPs, such as nucleolin and NM23-H2, which are of great significance in cancer treatment." (PMID 35625576, 2022). "The results show that nearly all the cancer-related malignant pathways (such as cell cycle, HIPPO, MYC, PI3K, and MYC), excluding the NRF2 signaling pathway, were significantly positively correlated with the HAscore." (PMID 35145517, 2022). "Among cancer-related signaling pathways with potential therapeutic targets, the RAS, NOTCH, WNT, Hippo, PI3K, and MYC pathways were predominantly affected." (PMID 36418292, 2022). "HIF-1 regulates expression of cancer stem cell markers like KLF4, MYC, OCT4, SOX2, and NANOG, and thus help cancer cells to survive through hypoxic crisis." (PMID 36253762, 2022). "By interfering with the PP2A-mediated dephosphorylation, SET activates oncogenic signaling such as AKT, ERK, c-MYC and GSK3-β to promote the survival and proliferation of cancer cells." (PMID 36345878, 2022). "Immunostaining for AR, CK8, high-molecular weight keratin (HMWCK), TOPK, c-MYC, and N-MYC demonstrated differential levels of CK8 and N-MYC in AP3 cancer and normal cells with HMWCK as a basal marker." (PMID 36970725, 2022). "OS PDXs also had increased MYC and RAD21 copy number gains (3–7 copies), both of which are known cancer markers with multi-functions leading to increased DNA replication and oncogenic-induced replication stress, a hallmark of aggressive OS." (PMID 36612255, 2022). "Among the selected cancer stemness genes, we found that TERT, MYC, CD44, BMI1, ABCB1 and ABCG2 were highly expressed in OCM1 cells compared to their expression in C918 cells, whereas the expression of ZEB1 was opposite to that of the stemness genes." (PMID 35404029, 2022). "KRT6A was reported to promote NSCLC cell growth and invasion through the MYC-regulated pentose phosphate pathway and to promote EMT and cancer stem cell transformation in LUAD." (PMID 36185621, 2022). "Based on these data, we found that the specific MYC enhancers R2 and R3 in HCC cell lines are significantly different from those in other cancers in terms of their location and activity." (PMID 35039581, 2022).